CLSPN (claspin)
Description:
Required for checkpoint mediated cell cycle arrest in response to inhibition of DNA replication or to DNA damage induced by both ionizing and UV irradiation. Adapter protein which binds to BRCA1 and the checkpoint kinase CHEK1 and facilitates the ATR-dependent phosphorylation of both proteins. Also required to maintain normal rates of replication fork progression during unperturbed DNA replication. Binds directly to DNA, with particular affinity for branched or forked molecules and interacts with multiple protein components of the replisome such as the MCM2-7 complex and TIMELESS. Important for initiation of DNA replication, recruits kinase CDC7 to phosphorylate MCM2-7 components.
Tractability: Small molecule: a structure with a bound ligand is known. PROTAC: UniProt records ubiquitination sites on it; ubiquitination databases record sites on it.
Gene: Protein-coding gene on chromosome 1 (35,720,218 to 35,770,002, reverse strand). Ensembl gene ENSG00000092853.
Subcellular location: Nucleus
Subcellular location (Human Protein Atlas): Golgi apparatus; Nucleoplasm
Pathways (Reactome):
Cell Cycle: Activation of ATR in response to replication stress
DNA Repair: Processing of DNA double-strand break ends
Metabolism of proteins: Ub-specific processing proteases
Programmed Cell Death: Apoptotic cleavage of cellular proteins
Gene Ontology:
Molecular function: anaphase-promoting complex binding; DNA secondary structure binding; protein binding
Biological process: DNA damage checkpoint signaling; DNA replication checkpoint signaling; mitotic DNA replication checkpoint signaling; mitotic G2 DNA damage checkpoint signaling
Cellular component: Golgi apparatus; nucleoplasm; nucleus
Genetic constraint (gnomAD): Loss-of-function variants: 52 observed, 128.21 expected, observed/expected ratio (o/e) 0.41, 90% interval 0.32 to 0.51. The upper end of that interval is the gene's LOEUF score, 0.51, which puts it in group 2 of 6, group 1 being the genes least tolerant of losing a copy. Missense variants: 1,228 observed, 1,446.6 expected, observed/expected ratio (o/e) 0.85, 90% interval 0.81 to 0.89. Synonymous variants: 470 observed, 511.75 expected, observed/expected ratio (o/e) 0.92, 90% interval 0.85 to 0.99.
Homologues: Orthologues: chimpanzee CLSPN (97% identical), macaque CLSPN (97% identical), rabbit CLSPN (86% identical), dog CLSPN (85% identical), guinea pig Clspn (83% identical), pig CLSPN (83% identical), rat Clspn (76% identical), mouse Clspn (75% identical), tropical clawed frog clspn (47% identical), Drosophila melanogaster Claspin (22% identical), Caenorhabditis elegans clsp-1 (13% identical).
Diseases named in the same sentence as CLSPN in open-access papers:
CLSPN is named in the same sentence as 65 diseases in open-access papers, as found by Europe PMC text mining. Sharing a sentence is not in itself a finding about the gene and the disease. The quoted sentences say what the papers report.
breast carcinoma (11 papers, 2012 to 2025). "We have shown that a CLSPN mutation associated with breast cancer (c.1574A>G; p.Asn525Ser) resulted in either Claspin degradation or decreased Chk1 phosphorylation and, as such, in deficient checkpoint activation." (PMID 41009395, 2025). "CLSPN c.1574A>G (p.Asn525Ser) was significantly associated with breast cancer and was shown to cause partial exon skipping and decreased Claspin expression and Chk1 activation in a minigene splicing assay and in signalling experiments, respectively." (PMID 32847043, 2020). "We also found that CLSPN c.1574A>G (p.Asn525Ser) was significantly associated with both familial and sporadic forms of breast cancer with an overrepresentation of the A allele." (PMID 32847043, 2020). "CLSPN c.2028+16G>A was significantly associated with familial breast cancer, with a higher frequency of the G allele among familial breast cancer cases when compared to controls." (PMID 32847043, 2020). "A CLSPN mutation c.1574A>G has been demonstrated to reduce CLSPN expression and activate Chk1, which may affect the CLSPN structure and function in breast cancer." (PMID 38256171, 2024). "We found several CLSPN variants associated with breast cancer and glioma." (PMID 32847043, 2020). "In this study, we have shown that Claspin variants may be associated with susceptibility to breast cancer and glioma development." (PMID 32847043, 2020). "Their homologs are significantly mutated (SRCAP in prostate cancer and glioblastoma; CLASPIN in gliomas and breast cancer) or overexpressed (H2A.Z in liver, colorectal, and metastatic breast cancer) in human cancers, and these alterations are predicted to play important roles in carcinogenesis." (PMID 30206225, 2018). "In this study, we characterized the spectrum of CLSPN genetic alterations present in breast cancer and glioma samples and cell lines, and assessed their association with cancer, as well as their possible functional consequences." (PMID 32847043, 2020). "We began by characterizing the spectrum of CLSPN germline alterations occurring in familial breast cancer (n = 147), sporadic breast cancer (n = 66) and in glioma (n = 53) patients." (PMID 32847043, 2020). "For that, DNA from breast cancer (familial and sporadic forms) and glioma patients, as well as DNA from blood samples of a group of healthy individuals, were screened for CLSPN genetic alterations." (PMID 32847043, 2020). "Our findings are mostly in agreement with recent data showing that claspin levels are higher in human colon, lung, bladder and breast carcinomas than in the corresponding autologous normal tissues, even though we did not analyze autologous normal tissues." (PMID 22731782, 2012). "On the other hand, NSC3852 may inhibit breast cancer cell proliferation by upregulating the expression of the apoptotic protein Claspin." (PMID 39859448, 2025). "Overexpression of CLSPN coding for Claspin was reported in ER- and/or PR- breast cancer." (PMID 33662042, 2021). "CLSPN c.2028+16G>A was significantly associated with familial breast cancer and glioma, whereas c.2230T>C (p.Ser744Pro), was exclusively detected in breast cancer and glioma patients, but not in healthy controls." (PMID 32847043, 2020). "Therefore, CLSPN germline alterations were characterized in sporadic and familial breast cancer and glioma samples, as well as in six cancer cell lines." (PMID 32847043, 2020). "Reducing expression of antiapoptotic regulators such as cIAP 1, Bcl-2, catalase,clusterin, HO-1, livin, XIAP, HSP27 and claspin was also demonstrated in human breast cancer line; the latter in support of mithochondrial apoptotic pathway using bromelain-based CHCT." (PMID 34466585, 2020).
breast carcinoma (continued). "However, the expression of claspin significantly increases in several human solid tumors such as in colon, lung, bladder and breast cancer." (PMID 22731782, 2012).
cervical cancer (6 papers, 2012 to 2025). A primary or metastatic malignant neoplasm involving the cervix. "In HeLa cells, human cervical cancer cell line, the effects of Claspin siRNA on Chk1 activation by various stresses were examined." (PMID 36671510, 2023). "We discovered three events in the genes ADAM10, RNPS1, and CLSPN that were previously reported to play a role in the progression or prognosis of cervical cancer." (PMID 37176052, 2023). "When we firstly evaluated claspin level in a series of different cell lines, we evidenced an up-regulation of the protein only in the cervical cancer cell lines SiHa, CaSki and HeLa." (PMID 22731782, 2012). "Furthermore, claspin expression is significantly high in cervical cancer cell and link to human papillomavirus-related high grade lesions of uterine cervix." (PMID 26496084, 2015). "Interestingly, recent in vitro data showed high claspin baseline level in cervical cancer cell lines." (PMID 22731782, 2012). "Furthermore, high levels of claspin have been found in cervical cancer cell lines." (PMID 22731782, 2012). "The authors provide evidence that both HPV-positive and negative cervical cancer cell lines show increased baseline levels of claspin." (PMID 22731782, 2012). "We found no claspin expression in the normal cell line and in the HK-168 cell line which has a basal/parabasal keratinocyte phenotype resembling the CIN2 stage, while its expression was evident in SiHa, CaSki and HeLa cervical carcinoma cell lines." (PMID 22731782, 2012).
gastric cancer (6 papers, 2019 to 2025). A primary or metastatic malignant neoplasm involving the stomach. "In gastric cancer, enhanced Claspin expression correlated with malignant histological parameters and with poor prognosis." (PMID 41009395, 2025). "Upregulated CLSPN was observed in patients with prostate cancer, renal cell carcinoma, gastric cancer, melanoma, anaplastic thyroid cancer and other malignant diseases or animal models." (PMID 37268895, 2023). "Due to its ability to inhibit the malignant characteristics of gastric cancer cells via the positive regulation of claspin, USP20 is considered to play a tumor-suppressing role in gastric cancer." (PMID 31208103, 2019). "Further, it has been shown that claspin expression in gastric cancer samples correlates with USP20 expression and that low claspin and USP20 levels are associated with worse overall survival." (PMID 31208103, 2019). "Analysis of Claspin expression datasets revealed that low levels of CLSPN transcripts were significantly associated with a poor prognosis in several types of cancer, namely breast, stomach, head and neck, rectal, and gastric cancer." (PMID 41009395, 2025). "In contrast, high Claspin and USP20 expression were correlated with enhanced overall survival, pointing to a protective role for Claspin and USP20 in gastric cancer." (PMID 41009395, 2025).
lung carcinoma (6 papers, 2014 to 2025). "Claspin over-expression (along with that of Tim and Chk1) was associated with reduced disease-free survival in low-grade lung cancer." (PMID 41009395, 2025). "Choi and colleagues found that Claspin was overexpressed in lung cancer brain metastasis that escaped radiotherapy." (PMID 41009395, 2025). "The authors observed that Claspin depletion enhanced radiation sensitivity in vitro in radioresistant lung cancer cells, but also in vivo using xenograft models of lung cancer brain metastasis." (PMID 41009395, 2025). "CLSPN expression was significantly increased in lung cancer cell lines, especially in PC9 and A549 cell lines." (PMID 37268895, 2023). "The expression of CLSPN in Beas2B cell line (Normal pulmonary epithelial cell) and 6 human lung cancer cell lines was detected by RT-qPCR." (PMID 37268895, 2023). "Here, we have monitored the expression of Claspin and Timeless in primary breast, colorectal, and lung cancers and compared it to other components of the ATR-CHK1 pathway." (PMID 30796221, 2019). "Depletion of TopBP1 or Claspin using shRNA showed an enhancement of sensitivity to radiation in radioresistant lung cancer cells (PC14PE6)." (PMID 25216549, 2014). "Consistently, depletion of TopBP1 or Claspin in lung cancer cells showed an enhancement of sensitivity to radiation." (PMID 25216549, 2014). "Target DEGs of miR-30c in our analysis were mostly related to the anti-apoptosis of abnormal tumor cells, including MAP3K9 in lung cancer, ST6GALNAC5 in prostate cancer, CSRNP3 in clear renal cell carcinoma, ZNF703 in breast tumors, and CLSPN in brain tumors." (PMID 36700234, 2022). "The upregulated expression of CLSPN and CDC25A is related to radioresistance in lung cancer." (PMID 33042838, 2020). "In addition, PCNA mRNA levels were only moderately increased (1.4-fold) in lung cancer compared to those of Claspin and CHK1 (4.5- and 4.4-fold, respectively), indicating that the increased expression of Claspin, Timeless, and CHK1 in cancer cells does not simply reflect increased proliferation." (PMID 30796221, 2019).
lymphoma (6 papers, 2022 to 2023). A malignant (clonal) proliferation of B- lymphocytes or T- lymphocytes which involves the lymph nodes, bone marrow and/or extranodal sites. "Subsequent examination of ATR/CHK1 signalling components revealed loss of expression of the ATR/CHK1 adaptor protein Claspin in RelA T505A Eμ-Myc lymphomas." (PMID 36240065, 2022). "The researchers found that Eμ-Myc lymphomas containing a RelA 505A mutation have decreased expression at the mRNA level of Claspin, an important protein that promotes Chk1 activity following replication stress." (PMID 36416754, 2022). "This suggested two distinct populations of WT Eμ-Myc lymphoma cells with high and low Claspin levels." (PMID 36240065, 2022). "By western blot we also see reduced Claspin protein levels in reimplanted RelA T505A lymphoma extracts." (PMID 36240065, 2022). "Western blot analysis confirmed that Claspin protein levels in WT lymphomas corresponded to mRNA levels and were also reduced in the Eμ-Myc/RelaT505A or Eμ-Myc/cRel−/− lymphomas, with the exception of one T505A sample." (PMID 36240065, 2022). "Western blot analysis confirmed reduced levels of Claspin protein in reimplanted Eμ-Myc/RelaT505A lymphomas, while in Eμ-Myc/cRel−/− extracts it was almost totally absent." (PMID 36240065, 2022). "We have also seen, using mice with either a c-Rel gene knockout or with a RelA Thr 505 to Ala mutation (RelAT505A), that both Eμ-Myc/cRel−/− and Eμ-Myc/RelAT505A lymphomas exhibit lower levels of Claspin mRNA and protein expression." (PMID 36240067, 2022). "Our analysis also revealed a high level of heterogeneity of Clspn mRNA expression in Eμ-Myc lymphoma cells, with many WT lymphomas showing similar levels of Claspin to those from Eμ-Myc/RelaT505A or Eμ-Myc/cRel−/− mice." (PMID 36240065, 2022). "Given the variability we see in primary WT lymphoma cells, we may, therefore, have inadvertently selected low Claspin expressing cells." (PMID 36240065, 2022). "We next investigated whether lower Claspin levels might contribute to the resistance to CCT244747 treatment we observed in the reimplanted Eμ-Myc/RelaT505A lymphomas." (PMID 36240065, 2022). "Consistent with our data from the Eμ-Myc model, these data suggest that reduced Claspin expression alone results in increased lymphoid hyperplasia that could contribute to the onset of lymphoma." (PMID 36240068, 2022). "However, we observed that Claspin expression was variable in primary WT Eμ-Myc lymphomas, with both high and low expressing sub-populations." (PMID 36240065, 2022). "In addition, since the NF-κB subunit, c-Rel has previously been shown to induce the expression of the ATR–CHK1 regulator Claspin in cell lines, we also included samples from primary c-Rel−/− Eμ-Myc lymphomas in this analysis as a control." (PMID 36240065, 2022). "This experiment, originally performed before our RNA Seq and proteomic analysis of reimplanted Eμ-Myc lymphomas was completed, revealed lower levels of Claspin mRNA and protein expression in primary RelA T505A Eμ-Myc lymphomas, while ATR, CHK1, ATRIP, RAD17 and TOPBP1 were unaffected." (PMID 36240065, 2022). "To conclude, we propose the use of canine lymphoma/leukemia cells as a model to study DDR in cancer, with ATR, Claspin, Chk1, and Rad51 as promising targets for further analysis." (PMID 37655260, 2023). "Therefore, a reduction in Claspin protein levels can account, at least in part, for the CCT244747 resistance we observe in reimplanted RelA T505A Eμ-Myc lymphomas." (PMID 36240065, 2022). "Since c-Rel has been described as an indirect regulator of CHK1 activity by inducing CLSPN gene expression, we were curious as to whether deleting c-Rel would affect ATR/CHK1 signalling in Eμ-Myc lymphomas and consequently the response to CHK1 inhibition." (PMID 36240066, 2022).
prostate carcinoma (6 papers, 2018 to 2025). A carcinoma that arises from epithelial cells of the prostate gland. "CLSPN knockdown significantly reduced the proliferative ability of renal cell carcinoma cells and prostate cancer cell lines, decreased migration and invasion, and promoted apoptosis." (PMID 41009395, 2025). "In vitro inhibition of Claspin expression decreased cell proliferation and stimulated apoptosis, features consistent with the role of Claspin in cell cycle checkpoint signaling and cell-fate decisions, and restored the sensitivity to treatment of docetaxel-resistant prostate cancer cells." (PMID 41009395, 2025). "Claspin has been described to be highly expressed in prostate cancer cells in comparison with non-cancerous prostate cells." (PMID 37655260, 2023). "However, the clinical significance of claspin in prostate cancer (PCa) has not been examined." (PMID 34240817, 2021).
B-cell lymphoma (5 papers, 2022 to 2025). "A proteome profiling carried out on BRCA1-mutated W780 and W0069 cells evidenced that CDDO-Im significantly increases caspase 3 cleavage, increases heat shock protein 70 (HSP70), and decreases in claspin, BIRC5, B-cell Lymphoma-extra-large, and BCL2 associated agonist of cell death." (PMID 40136510, 2025).
glioblastoma (5 papers, 2018 to 2025). The most malignant astrocytic tumor (WHO grade IV). "For instance, an endogenous circRNA derived from exons 11–14 of CLSPN (hsa_circ_0011591, circCLSPN) has been implicated in glioblastoma multiforme (GBM) development." (PMID 41009395, 2025). "USP3 has the capability to interact with Claspin via the UCH domain for the purpose of deubiquitinating it, resulting in the activation of Claspin-dependent ATR-Chk1 signaling that ultimately contributes to the augmentation of glioblastoma radiation resistance." (PMID 38773075, 2024). "CLSPN may be a potential therapeutic target for glioblastoma." (PMID 36092717, 2022). "Moreover, increased USP3 transcriptionally modulated by Smoothened (Smo) reduces Claspin polyubiquitination and proteasomal degradation, leading to activation of Claspin-dependent ATR-CHK1 signaling and radiation resistance of glioblastoma (GBM)." (PMID 36694209, 2023).
glioma (5 papers, 2018 to 2025). A benign or malignant brain and spinal cord tumor that arises from glial cells (astrocytes, oligodendrocytes, ependymal cells). "Based on these data, the authors suggested that CLSPN could act as an oncogene with strong prognosis and diagnostic value in low-grade glioma." (PMID 41009395, 2025). "In low-grade glioma, high Claspin levels correlated with malignant histological characteristics and reduced overall survival, and were an independent risk factor for survival." (PMID 41009395, 2025). "In recent years, researchers have begun to study the role of the CLSPN gene in cancer development, specifically after finding high levels of CLSPN in cancers as diverse as breast, ovarian, cervical, glioma, non-small cell lung cancer and renal cell carcinoma." (PMID 38256171, 2024).